FPR2 (formyl peptide receptor 2)
Diseases named in the same sentence as FPR2 in open-access papers (continued):
Sharing a sentence is not in itself a finding about the gene and the disease.
dengue disease (1 paper, 2022). Dengue fever (DF), caused by dengue virus, is an arboviral disease characterized by an initial non-specific febrile illness that can sometimes progress to more severe forms manifesting capillary leakage and hemorrhage (dengue hemorrhagic fever, or DHF) and shock (dengue shock syndrome, or DSS). "We have thereby identified that altered levels of the pro-resolving mediator AnxA1 are of pathological relevance in DENV infection, suggesting FPR2/ALX agonists as a therapeutic target for dengue disease." (PMID 35293862, 2022). "The present study confirmed that dengue disease is associated with increased plasma levels of MCPT-1 and identified enhanced secretion in animals lacking AnxA1 or FPR2/ALX." (PMID 35293862, 2022). "Despite the limitations of modelling dengue disease in immunocompetent animals, infection of AnxA1 KO and FPR2 KO animals (and their respective littermates BALB/c and C57BL/6 mice) with high inoculum of DENV-2 was applied to investigate the role of endogenous AnxA1/FPR2 in dengue disease." (PMID 35293862, 2022).
dry eye (1 paper, 2023). "Previous studies have reported that FPR2 can reduce hyperosmolarity-induced NETosis, which helps alleviate dry eye." (PMID 37941896, 2023).
gestational diabetes (1 paper, 2022). Carbohydrate intolerance first diagnosed during pregnancy. "FPR2 increased significantly in gestational diabetes mellitus (GDM) and might be used as a marker for the prevention, clinical treatment and drug design of GDM." (PMID 35018584, 2022).
glomerulopathy (1 paper, 2018). "FPR2 is found in adipose tissues as a receptor for the pro-resolving mediators, which contribute to the restoration of in adipose inflammation and treatment of obesity-related glomerulopathy." (PMID 30029622, 2018).
gram-positive bacterial infections (1 paper, 2012). Infections caused by bacteria that retain the crystal violet stain (positive) when treated by the gram-staining method. "Notably, our data underscore the importance of FPR2/ALX in Gram-positive bacterial infections and indicate that FPR2/ALX should be considered as a target for anti-infective and anti-inflammatory therapies." (PMID 22768166, 2012).
Hypertension (1 paper, 2019). The presence of chronic increased pressure in the systemic arterial system. "OSA patients with hypertension had decreased FPR2 expressions on neutrophil and FPR3 expressions of NK cell." (PMID 31116781, 2019). "In the present study, we found that FPR2 expression on neutrophil was decreased in OSA patients and further decreased in those with hypertension." (PMID 31116781, 2019). "Furthermore, we found increased FPR1/FPR2 ratio and insufficiency of FPR2 and FPR3 in the OSA patients with EDS and hypertension phenotypes, respectively, while long-term CPAP treatment decreased FPR1 expression and FPR1/FPR2 expression ratio, and increased FPR3 and FPR2 expression." (PMID 31116781, 2019). "We have found a link of FPR1 over-expression and FPR2 under-expression on blood neutrophil along with defective production of LXA4/RvD1, as well as FPR3 insufficiency of M1 monocyte, M2a monocyte, and NK cell, to OSA and its adverse consequences, including hypertension and EDS." (PMID 31116781, 2019).
invasive breast carcinoma (1 paper, 2017). A carcinoma that infiltrates the breast parenchyma. "Due to their tissue expression in invasive breast cancer, ANXA1 and FPR2 have become a target for drug discovery." (PMID 29263330, 2017).
keratitis (1 paper, 2020). A corneal disease that is characterized by inflammation of the cornea. "The results seem to be consistent with the hypothesis that RvD1 protected the cornea from the LPS‐induced keratitis by acting on several inflammatory components of this damage, pivoted by FPR2 activation and macrophages‐leucocytes activity." (PMID 33058526, 2020).
kidney damage (1 paper, 2021). "Along these lines, the inhibition of ALX/FPR2 axis aggravated sepsis-induced kidney damage." (PMID 34769064, 2021).
latent infection (1 paper, 2024). "This analysis revealed that patients with active TB expressed higher levels of FPR1 and FPR2 compared to those with latent infection, suggesting that these receptors are induced by Mtb infection, and their expression correlates with symptomatic disease." (PMID 38853986, 2024).
liver cancer (1 paper, 2023). An epithelial or non-epithelial malignant neoplasm that arises from the liver. "FPR2 agonists have consistently been shown to suppress liver cancer progression, suggesting that FPR2 agonists may represent potential candidates for the treatment of liver cancer." (PMID 36750693, 2023). "However, data demonstrating the action of FPR2 agonists in preventing HCC progression are limited, and further study is required to support their role in HCC before targeting them as therapeutics for liver cancer." (PMID 36750693, 2023).
liver diseases (1 paper, 2023). "FPR2 has anti-inflammatory properties and attenuates the progression of liver disease, as supported by the results obtained from experiments with Fpr2-depleted mice." (PMID 36750693, 2023). "Several studies have reported that the anti-inflammatory ligands of FPR2 alleviate liver disease." (PMID 36750693, 2023). "In addition, we focus on the pathophysiological role of FPR2 in inflammation-related liver disease and suggest its therapeutic potential." (PMID 36750693, 2023). "Therefore, it is important to understand FPR2’s function per se and to elucidate the mechanism underlying immunomodulation initiated by ligand-activated FPR2 before suggesting FPR2 as a novel therapeutic agent for liver diseases." (PMID 36750693, 2023).
lung adenocarcinoma (1 paper, 2023). A carcinoma that arises from the lung and is characterized by the presence of malignant glandular epithelial cells. "In lung adenocarcinoma, the immune stemness genes Interleukin-6 (IL-6), Formyl peptide receptor 2 (FPR2) and Relaxin-3 (RLN3) can play an important role in tumor development through cytokine-cytokine receptor interactions and neuroactive ligand-receptor interactions." (PMID 38037058, 2023).
lymph node metastasis (1 paper, 2017). "Since FPR2 expression was associated with invasion depth and lymph node metastasis in GC specimens, we then evaluated the abilities of migration and invasion of GC cells in vitro." (PMID 28600569, 2017). "In this study, we found that the levels of FPR2 expression in GC were positively correlated with invasion depth, lymph node metastasis and negatively correlated with the patients’ overall survival." (PMID 28600569, 2017). "We found that FPR2 was expressed more frequently in GC cancerous tissues than in adjacent tissues and increased expression levels in cancerous tissues were correlated with the invasion depth and lymph node metastasis as well as the poor survival of the patients." (PMID 28600569, 2017).
metastasis (1 paper, 2022). The spread or migration of cancer cells from one part of the body (where they first appeared) to another. "The association between lymph node positive recurrence-free patient survival and distant metastasis-free patient survival and ANXA1 and FPR1 and FPR2 expression was examined using TCGA datasets." (PMID 35382852, 2022).
neuropathic pain (1 paper, 2023). Chronic pain caused by damage to nerve fibers. "Fpr2 is downregulated in the rat model (fold change = − 1.35, p = 0.002) and increased in neuropathic pain patients (fold change = 1.33, Bonferroni-corrected p = 0.00278)." (PMID 36422814, 2023).
non-alcoholic steatohepatitis (1 paper, 2022). "The endogenous ligand for FPR2, annexin A1, has also shown beneficial effects in reducing fibrosis in a mouse model of non-alcoholic steatohepatitis (NASH), while the Annexin A1 derived peptide Ac2-26 reduced collagen deposition in a model of silicosis." (PMID 36793548, 2022).
ovarian tumors (1 paper, 2022). "To be positive that ovarian tumors express the receptors to mediate the SPM signaling, we tested for the expression of FPR2 (RvD1 receptor) and Chem23R (RvE1 receptor), which were both expressed in the CaOV3 tumors." (PMID 35326656, 2022).
post-streptococcal glomerulonephritis (1 paper, 2014). "Indeed, increased levels of the proresolving mediator LXA4 and FPR2/ALX are detected in human pathologies, including RA and acute post-streptococcal glomerulonephritis, suggesting that protective mediators and their receptors are may be operative within inflammatory settings to aid resolution." (PMID 24993159, 2014).
psoriasis (1 paper, 2020). An autoimmune condition characterized by red, well-delineated plaques with silvery scales that are usually on the extensor surfaces and scalp. "These confirm the association of cathelicidins and the involvement of FPR2/ALX-mediated signalling in psoriasis." (PMID 32887440, 2020). "Further research is required to determine the significance of inflammatory molecules other than LL37 and receptors other than FPR2/ALX in the modulation of platelet activation during psoriasis." (PMID 32887440, 2020). "This suggests the involvement of FPR2/ALX signalling in the LL37/mCRAMP-induced platelet activation during the pathogenesis of psoriasis." (PMID 32887440, 2020). "This study reveals the clinical significance of mCRAMP in the augmentation of platelet reactivity during psoriasis via Fpr2/3." (PMID 32887440, 2020). "Together, these data demonstrate the involvement of FPR2/ALX in the development of pathogenesis and thrombotic/other platelet-mediated complications during psoriasis." (PMID 32887440, 2020).
pulmonary hypertension (1 paper, 2022). Increased pressure within the pulmonary circulation due to lung or heart disorder. "In addition, in this experiment, changes in pulmonary hypertension, FPR2 level in the heart tissue, and effects of FPR2 over-expressing was not delineated, and the sex variation for the in vivo models was also not investigated, and which need further studies." (PMID 36142517, 2022).
pulmonary sarcoidosis (1 paper, 2024). Sarcoidosis affecting the lung parenchyma. "CTSS, CYBB, FPR2, MNDA, TLR1, and TLR8 could be conducive to improving the diagnostic process and understanding the underlying mechanisms of pulmonary sarcoidosis, and were further verified in PBMC samples using qRT-PCR." (PMID 39364409, 2024). "CTSS, CYBB, FPR2, MNDA, TLR1, and TLR8 could be conducive to improving the diagnostic process and understanding the underlying mechanisms of pulmonary sarcoidosis." (PMID 39364409, 2024).
pulmonary TB (1 paper, 2024). "We observed that expression levels of FPR1 and FPR2 in peripheral blood cells were elevated in patients with active pulmonary TB compared to healthy controls (HCs)." (PMID 38853986, 2024).
renal fibrosis (1 paper, 2021). A final common manifestation of a wide variety of chronic kidney diseases characterized by glomerulosclerosis and tubulointerstitial fibrosis. "Interestingly, the RvD1-ALX/FPR2 axis inhibited TNF-α receptor signaling and renal fibrosis." (PMID 34769064, 2021).
respiratory infections (1 paper, 2018). "Targeting Fpr2 with pro-resolving eicosanoids such as AT-RvD1 may restore microglial homeostasis during severe respiratory infections." (PMID 29980196, 2018).
sarcoidosis (1 paper, 2024). Sarcoidosis is a multisystemic disorder of unknown cause characterized by the formation of immune granulomas in involved organs. "Besides exogenous triggers, FPR2 could bind self-compounds such as serum amyloid A (SAA), crucial in the progression of sarcoidosis." (PMID 39364409, 2024).
schwannoma (1 paper, 2020). A benign, usually encapsulated slow growing tumor composed of Schwann cells. "On the other hand, 10 nM and 100 nM fMLF stimulation upregulated Fpr2 in RT4 schwannoma cells, and also increased levels of chemokine receptor CCR2 and CXCR4 as well as PKCβ." (PMID 33322305, 2020). "We studied RT4 schwannoma cells to investigate the regulation of Fpr2 and TLR9 after stimulation with fMLF as a prototypical formylated peptide." (PMID 33322305, 2020). "RT4 schwannoma cells were used as an experimental in vitro model for Schwann cells to study the effect of fMLF on the regulation of Fpr2 and TLR9—receptors for mitochondrial peptides and DNA, respectively." (PMID 33322305, 2020). "We analyzed Fpr2 protein levels in whole-cell lysate prepared from RT4 schwannoma cells by Western blots using a commercially available rabbit polyclonal antibody (NLS1878, Novus Biologicals, Centennial, CO, USA) detecting a protein band at 38 kDa corresponding to the molecular weight of Fpr2." (PMID 33322305, 2020). "RT4 schwannoma cells were used as an in vitro model of Schwann cells to investigate the course of cytoplasmic events following stimulation of fMLF and CpG —ligands for Fpr2 and TLR9, respectively." (PMID 33322305, 2020). "From these results using an in vitro RT4 schwannoma model, we can assume that chemokine receptors CCR2 and CXCR4 may serve as co-receptors of Fpr2 when Schwann cells of the distal nerve stump are stimulated with formylated peptides released from injured axons." (PMID 33322305, 2020). "Although we used a specific anti-Fpr2 antibody, we cannot rule out a contribution of Fpr1 in the reaction of RT4 schwannoma cells to the fMLF effect." (PMID 33322305, 2020).
sickle cell disease (1 paper, 2025). Sickle cell anemias are chronic hemolytic diseases that may induce three types of acute accidents: severe anemia, severe bacterial infections, and ischemic vasoocclusive accidents (VOA) caused by sickle-shaped red blood cells obstructing small blood vessels and capillaries. "Interestingly, Ansari's research on sickle cell disease revealed that ANXA1‐induced activation of macrophage FPR2/ALX axis, leading to differentiation of M2 polarisation and conferring a protective effect." (PMID 39993960, 2025).
Sleep disordered breathing (1 paper, 2019). "For the first time, we found defective LXA4 and RvD1 production in association with increased FPR1/FPR2 expression ratio on blood neutrophils in patients with sleep disordered breathing." (PMID 31116781, 2019). "Sleep disordered breathing patients with excessive daytime sleepiness had significantly increased FPR1/FPR2 expression ratio on neutrophil (0.86±0.47, n = 23) as compared with those without excessive daytime sleepiness (0.62±0.28, n = 39, adjusted p = 0.041)." (PMID 31116781, 2019).
status epilepticus (1 paper, 2018). Status epilepticus is defined as a continuous seizure lasting more than 30 min, or two or more seizures without full recovery of consciousness between any of them. "ALXR/FPR2 induction was measured at 24 h post-status epilepticus therefore anticipating ChemR23/ERV1 increase." (PMID 30307467, 2018).
temporal lobe epilepsy (1 paper, 2025). A localization-related (focal) form of epilepsy characterized by recurrent seizures that arise from foci within the temporal lobe, most commonly from its mesial aspect. "Pro-resolving receptors such as ALX/FPR2 and ChemR23 were also found upregulated in astrocytes from epileptogenic tissue of both mice and patients with temporal lobe epilepsy, underscoring the translational relevance of these mechanisms." (PMID 41373540, 2025).
tuberculosis (1 paper, 2024). A chronic, recurrent infection caused by the bacterium Mycobacterium tuberculosis. "This study investigates the functions of Fpr1 and Fpr2 in defense against Mycobacterium tuberculosis (Mtb), the causative agent of TB." (PMID 38853986, 2024).
urothelial carcinoma (1 paper, 2025). A malignant neoplasm derived from the transitional epithelium of the urinary tract (urinary bladder, ureter, urethra, or renal pelvis). "In the PPI network specific to nonpapillary urothelial carcinoma, network B, we identified GNB1, RHOA, UBC, and FPR2 as hub proteins, which were involved in the PI3K/AKT signaling pathway." (PMID 41342186, 2025).
Whipple disease (1 paper, 2010). A systemic infection caused by the Gram-positive bacterium Tropheryma whipplei. "As FPR2 mediates the chemotactic activity of a variety of pathogen and host-derived peptides, it may actively participate in the macrophage infiltration observed in Whipple's disease lesions." (PMID 20090833, 2010).
xerostomia (1 paper, 2016). Dryness of the mouth resulting from reduced salivary secretion. "Overall, our data suggest that the loss of ALX/FPR2 results in unresolved acute inflammation and SMG dysfunction (xerostomia) in response to LPS that is similar to human salivary gland dysfunction induced by bacterial infection." (PMID 27064029, 2016).